MLF1 (myeloid leukemia factor 1)
Diseases named in the same sentence as MLF1 in open-access papers:
MLF1 is named in the same sentence as 41 diseases in open-access papers, as found by Europe PMC text mining. Sharing a sentence is not in itself a finding about the gene and the disease. The quoted sentences say what the papers report.
myelodysplastic syndrome (14 papers, 2010 to 2024). A clonal hematopoietic disorder characterized by dysplasia and ineffective hematopoiesis in one or more of the hematopoietic cell lines. "MLF1 was first identified from a chromosomal rearrangement that caused acute myeloid leukemia and myelodysplastic syndrome, and functioned in the regulation of primitive hematopoietic cell development." (PMID 36733771, 2022). "Translocation between MLF1 and the nucleophosmin has been associated with myelodysplastic syndrome and acute myeloid leukemia." (PMID 34503158, 2021). "Translocations between MLF1 and nucleophosmin have been associated with myelodysplastic syndrome (MDS) and acute myeloid leukemia (AML)." (PMID 29340074, 2017). "Mlf1 (myeloid leukemia factor 1) is associated with myeloid leukemia; Mlf1 is fused to nucleophosmin (Npm1) in 1% of acute myeloid leukemia (AML) cases and is overexpressed in 25% of cases of AML associated with myelodysplastic syndrome." (PMID 23300604, 2012). "While normal hematopoietic tissue does not express MLF1, approximately a quarter of high-risk myelodysplastic syndrome and MDS-associated AML show overexpression of MLF1." (PMID 38443661, 2024).
acute myeloid leukemia (11 papers, 2012 to 2024). Acute myeloid leukemia (AML) is a group of neoplasms arising from precursor cells committed to the myeloid cell-line differentiation. "Mlf1 is a soluble protein of nuclear and cytosolic localization, which was originally identified in chromosomal translocations that lead to acute myeloid leukemia." (PMID 39432513, 2024). "Human Mlf1 was originally identified as part of the leukemic fusion protein NPM-MLF1, generated by chromosomal translocation in patients with acute myeloid leukemia." (PMID 39432513, 2024).
leukemia (6 papers, 2016 to 2024). A malignant (clonal) hematologic disorder, involving hematopoietic stem cells and characterized by the presence of primitive or atypical myeloid or lymphoid cells in the bone marrow and the blood. "Reasonably, it can be inferred that MLF1 is a context-dependent gene, with its elevated expression being associated with leukemia promotion and suppression in different settings." (PMID 36814822, 2023). "DCAF8 further promotes the degradation of myeloid leukemia factors 1 and 2 (MLF1,2), two factors that are associated with leukemia and several other malignancies, through the ubiquitin-proteasome system." (PMID 36831395, 2023). "Chimeric proteins between NPM1 and the retinoic acid receptor-α gene (RARα) or between NPM1 and the myelodysplasia/myeloid leukemia factor 1 (MLF1) have also been reported in rare cases of leukemia." (PMID 27553022, 2016). "Importantly, five out of six mice transplanted with NPM1::CCDC28A-expressing cells and two out of twelve mice transplanted with NPM1::MLF1-expressing cells developed leukemia within 6 months after transplantation." (PMID 39443736, 2024). "It is reasonable to conclude that MLF1 functions as a tumor suppressor gene in leukemia." (PMID 36814822, 2023). "However, it does not always appear to be a protective factor, and when leukemia is developed, MLF1 is positively correlated with leukemia." (PMID 36814822, 2023). "NPM1::CCDC28A-expressing cells were enriched in a ckit+ granulocytic-monocytic progenitor (GMP)-like population known to contain leukemia stem cells, whereas NPM1::MLF1-expressing cells produced diverse cell types, including Gr1+ mature myeloid cells." (PMID 39443736, 2024). "Further study has indicated that MLF1 impairs RUNX1-ETO accumulation and reduces RUNX1-ETO-dependent leukemia cell proliferation." (PMID 36814822, 2023). "Although the role of NPM in the pathogenesis of leukemia has been well studied, the contribution of MLF1 to normal hematopoiesis and oncogenesis has not been adequately characterized." (PMID 36814822, 2023).
gastric cancer (4 papers, 2017 to 2023). A primary or metastatic malignant neoplasm involving the stomach. "There is a possibility that MLF1 silencing is causally related to the development and progression of gastric cancer." (PMID 36814822, 2023). "MLF1 is methylation-silenced in the gastric cancer cell line and is upregulated 27-fold after 5-AZA-dC treatment." (PMID 36814822, 2023). "The study found that six genes (MINT25, RORA, GDNF, ADAM23, PRDM5, MLF1) presented differential methylation between gastric cancer and normal mucosa in the training and test population." (PMID 32489454, 2020).
neuroblastoma (3 papers, 2017 to 2024). Neuroblastoma (NB) is the most common solid, extracranial childhood tumor. "We further demonstrate that neuroblastoma cells homozygous for the risk allele at 3q25 express higher levels of MLF1 and that silencing of MLF1 in neuroblastoma cells results in significant growth inhibition." (PMID 28545128, 2017). "Taken together, we show that common DNA variants within CPZ at 4p16 and upstream of MLF1 at 3q25 influence neuroblastoma susceptibility and MLF1 likely plays an important role in neuroblastoma tumorigenesis." (PMID 28545128, 2017). "Increased expression of MLF1 was observed in neuroblastoma cells homozygous for the rs6441201 risk allele (P = 0.02), and significant growth inhibition was observed upon depletion of MLF1 (P < 0.0001) in neuroblastoma cells." (PMID 28545128, 2017). "However, MLF1 expression was significantly higher in neuroblastoma cells harboring the rs6441201 risk allele compared those homozygous for the protective allele (P = 0.02)." (PMID 28545128, 2017). "Taken together, these data are consistent with the hypothesis that MLF1 promotes neuroblastoma tumorigenesis, and that the 3q25 risk alleles are associated with growth advantage through increased MLF1 expression." (PMID 28545128, 2017). "An extensive genome-wide association study (GWAS) has indicated that MLF1 expression is high in neuroblastoma and that silenced MLF1 significantly suppresses tumor proliferation." (PMID 36814822, 2023). "Silencing of MLF1 resulted in significant growth inhibition in four distinct neuroblastoma cell lines." (PMID 28545128, 2017). "Ongoing studies will further elucidate the role of both CPZ and MLF1 in neuroblastoma tumorigenesis." (PMID 28545128, 2017). "Given that the observed cell growth phenotype was independent of rs6441201 genotype, alternative mechanisms driving MLF1 expression to promote neuroblastoma cell growth likely exist." (PMID 28545128, 2017). "However, MLF1 expression was observed in nineteen distinct neuroblastoma cell lines interrogated in this study, with the highest expression in cells homozygous for the risk allele at rs6441201." (PMID 28545128, 2017).
acute promyelocytic leukemia (2 papers, 2022 to 2024). An aggressive form of acute myeloid leukemia (AML), characterized by arrest of leukocyte differentiation at the promyelocyte stage, due to a specific chromosomal translocation t(15;17) in myeloid cells. "Chromosomal translocations may result in oncogenic fusion proteins, such as NPM-ALK in anaplastic large cell lymphoma, NPM-RARα (retinoic acid alpha) in acute promyelocytic leukemia (APL), and NPM-MLF1 (myelodysplasia/myeloid leukemia factor 1) in MDS and AML." (PMID 35054502, 2022).
Myelodysplasia (2 papers, 2016 to 2021). Clonal hematopoietic stem cell disorders characterized by dysplasia (ineffective production) in one or more hematopoietic cell lineages, leading to anemia and cytopenia. "It produces a fusion of 5’ coding sequences of the nucleophosmin (NPM1) gene at 5q35 and the myelodysplasia/myeloid leukemia factor 1 (MLF1) gene on 3q25, producing an NPM1-MLF1 in-frame chimeric gene." (PMID 34204358, 2021).
myeloid leukemia (2 papers, 2012 to 2013). A clonal proliferation of myeloid cells and their precursors in the bone marrow, peripheral blood, and spleen. "Of note is that chromosomal translocation produces a fusion protein of MLF1 with NPM, and is significantly associated with myelodysplastic syndoromes (MDS), followed by myeloid leukemia." (PMID 23776465, 2013).
myeloid neoplasm (2 papers, 2024). Proliferation of myeloid cells originating from a primitive stem cell. "Indeed, at least one pathogenic mutation (WT1, FLT3-ITD, IDH2 or PTPN11 mutation) has been identified in all the reported myeloid tumors harboring NPM1::MLF1." (PMID 39443736, 2024).
cardiac hypertrophy (1 paper, 2025). "In contrast, MLF1 expression was found to be downregulated in in vivo models of cardiac hypertrophy induced by pressure overload or neurohumoral stimulation, as well as upon mechanical stretch in NRVCM." (PMID 41590846, 2025). "These opposing effects suggest that MLF1 and MLF2 may have antagonistic roles in cardiac hypertrophy." (PMID 41590846, 2025). "Supporting this notion, we observed that MLF1 overexpression downregulated MLF2 expression, and vice versa, indicating an inverse regulation that may have functional relevance in the context of cardiac hypertrophy." (PMID 41590846, 2025).
cholestasis (1 paper, 2025). Impairment of the bile flow caused by obstruction within the liver, or outside the liver in the bile duct system. "Diseases that were significantly associated with CXCL2 include cholestasis, inflammation, acute lung injury, pulmonary fibrosis and hypertension, and those that were significantly associated with MLF1 was stomach neoplasms." (PMID 41378129, 2025).
cyst (1 paper, 2016). A sac-like closed membranous structure that may be empty or contain fluid or amorphous material. "Here we identify Mlf1-adaptor molecule (Madm), a novel tumour suppressor that regulates the competition between germline stem cells (GSCs) and somatic cyst stem cells (CySCs) for niche occupancy." (PMID 26792023, 2016).
desminopathies (1 paper, 2025). "Notably, Mlf2, an interaction partner of Mlf1, has been shown be enriched in protein aggregates in human desminopathies thus highlighting a novel and conceivable disease link between Mlf1 and Mlf2 related transcriptional control and Dnajb6 and Bag3 mediated protein quality control." (PMID 41165044, 2025).
erythroleukemia (1 paper, 2023). Acute erythroid leukemia characterised by the presence of at least 50% erythroid precursors and at least 20% myeloblasts in the bone marrow. "A preclinical study has confirmed that MLF1 expression drives the occurrence of erythroleukemia." (PMID 36814822, 2023).
Huntington disease (1 paper, 2024). Huntington disease (HD) is a rare neurodegenerative disorder of the central nervous system characterized by unwanted choreatic movements, behavioral and psychiatric disturbances and dementia. "The protein aggregates formed in Huntington’s disease were shown to contain Mlf1, but overexpression of Mlf1 or Mlf2 leads to the release of proteins from these aggregates." (PMID 39432513, 2024).
intrahepatic cholangiocarcinoma (1 paper, 2025). A carcinoma that arises from the intrahepatic bile duct epithelium in any site of the intrahepatic biliary tree. "In intrahepatic cholangiocarcinoma (ICC), the upregulation of myeloid leukemia factor 1 (MLF1) is significantly correlated with the upregulation of MUC1 expression involving the EMT of cancer progression." (PMID 40699805, 2025).
lung adenocarcinoma (1 paper, 2020). A carcinoma that arises from the lung and is characterized by the presence of malignant glandular epithelial cells. "Prof. Xiao-jing Wang found that MLF1 promotes the proliferation and colony-forming abilities of lung adenocarcinoma cells and significantly decreases apoptosis in vitro." (PMID 33224985, 2020).
lung squamous cell carcinoma (1 paper, 2017). "MLF1 is overexpressed in more than 25% of MDS-associated cases of AML, in the malignant transformation phase of MDS, and in lung squamous cell carcinoma." (PMID 28545128, 2017).
mantle cell lymphoma (1 paper, 2023). Mantle cell lymphoma is a rare form of malignant non-Hodgkin lymphoma affecting B lymphocytes in the lymph nodes in a region called the ``mantle zone''. "Hypermethylated MLF1 gene in mantle cell lymphoma (MCL) has been confirmed by genome-wide DNA methylation analysis, and aberrant methylation is associated with inverse changes in mRNA levels." (PMID 36814822, 2023).
nasopharyngeal carcinoma (1 paper, 2023). A carcinoma arising from the nasopharyngeal epithelium. "have found that the expression levels of MLF1 were downregulated in tumor tissues compared to normal tissues, which suggested that MLF1 influences tumor initiation and progression in nasopharyngeal carcinoma." (PMID 36814822, 2023).
prostate carcinoma (1 paper, 2021). A carcinoma that arises from epithelial cells of the prostate gland. "Interestingly, other oncogenic factors not previously implicated in prostate cancer also exhibited 5′-UTR mutations including MECOM and MLF1." (PMID 34244513, 2021).
tumor (13 papers, 2010 to 2025). "Studies have shown that MLF1 plays a critical role in tumor initiation and progression across various cancer types." (PMID 41378129, 2025). "It is worth mentioning that MLF1 is a positive factor in various biological processes, such as progenitor cell development and tumor regression." (PMID 36814822, 2023). "MLF1 has so far been shown to be a double-edged sword, acting as either a tumor suppressor or an oncogene, depending on the context of the cell." (PMID 36814822, 2023). "Multiple tumor driver genes that are associated with spermatogenesis pathway such as mTOR, EZH2, NF2, DCC and MLF1 had high enrichment score in the EGFR group." (PMID 35428753, 2022). "We also found that the expression levels of GLB1L and MLF1 were downregulated in tumor tissues relative to normal tissues, which suggested that both of them influence tumor initiation and progression in NPC." (PMID 34692486, 2021). "In certain types of tumors, alterations in MLF1 expression levels have been observed, which may correlate with tumor malignancy, prognosis, and therapeutic outcomes." (PMID 41378129, 2025). "Modulating the expression or function of MLF1 could potentially provide novel insights and strategies for tumor treatment." (PMID 41378129, 2025). "As a promising target for tumor therapy, MLF1 has garnered significant attention." (PMID 41378129, 2025). "Based on the studies conducted so far, MLF1 may act as both a tumor suppressor and tumor oncogene, depending on the context of the cell." (PMID 36814822, 2023). "MLF1 treatment upregulates the level of C/EBPα by suppressing Trib1 or RUNX1-ETO, which causes the inactivation of myeloid-derived suppressor cells (MDSCs) with potent antitumor responses across different tumor models and cancer patients." (PMID 36814822, 2023). "In addition, some genes (MLF1, SNORA20) are associated with carcinogenesis, and are considered as tumor markers." (PMID 33121152, 2020). "The opposing effects of Madm and Mlf1 on M1 cell differentiation suggest that Madm may function as a tumour suppressor." (PMID 26792023, 2016). "Indeed, TSC22 family members have been shown in Drosophila to be part of a growth-promoting signaling complex involving the Mlf1 adapter molecule Madm, and a TSC22D1/D4 complex has been implicated in BRAF-induced senescence and neoplasia." (PMID 23307490, 2013). "Further findings suggested that MLF1 could act as an oncogene or a tumor suppressor depending on the cell context and it was shown that MLF1 overexpression either impairs cell cycle exit and differentiation, promotes apoptosis, or inhibits proliferation in different cultured cell lines." (PMID 28742844, 2017). "We find that the 214 entropy elevated and average-methylation stable genes (Q1) are not significantly repressed in the tumor uterus sample compared to the matched normal sample (p value = 0.2), and that the single known TSG (MLF1) in the Q1 group can also be detected by methylation concurrence." (PMID 34489442, 2021).
cancer (11 papers, 2014 to 2025). A tumor composed of atypical neoplastic, often pleomorphic cells that invade other tissues. "Since both RSRC1 and MLF1 have been previously implicated in cancer, we investigated the 3q25 locus in more detail." (PMID 28545128, 2017). "The fourth case (BR4) harboured 22 mutations affecting cancer‐associated genes and a MLF1 deletion as its only CNA." (PMID 26205622, 2015). "In total, 224 different cancer-related genes were found to span the CTLPs, wherein MLF1 was most common in 7/64 CTLPs." (PMID 32409713, 2020). "MLF1’s lowest expression was marvellously in AML among various cancers, and its expression level in THCA was obviously higher than in AML." (PMID 29340074, 2017). "Just like SDC4, MLF1 also occupied a critical position in the network and had more interactions than the average gene, which are common characteristics of cancer driver genes." (PMID 29340074, 2017). "MLF1 is found in many cells, including blood, nerve, and cancer cells." (PMID 41378129, 2025). "Although MLF1 and SDC4 were generally highly expressed in multiple types of cancers, their expression levels varied over a large range." (PMID 29340074, 2017). "MLF1 was moderately expressed (mean FPKM = 233.73), while SDC4 was apparently highly expressed (mean FPKM = 19772.64) in THCA, among various cancers." (PMID 29340074, 2017). "The PCC between MLF1 or SDC4 and LA16c-380H5.2 was 0.779 (P = 3.62E-13) and 0.85 (P = 1.77E-17), respectively, from normal samples and 0.058 (P = 0.194) and 0.35 (P = 5.87E-16) for the cancer group; both PCC values fell considerably." (PMID 29340074, 2017). "A uniquely enriched pathway of all five PCGs (FSTL3, KLF6, MLF1, NR4A3, and SDC4) was “Transcriptional misregulation in cancer” (P = 0.048), suggesting that those five PCGs and their regulating lncRNAs may play roles in transcriptional regulation levels in THCA." (PMID 29340074, 2017).
genetic disorders (1 paper, 2025). "Regulating the expression level or function of MLF1 may offer new gene therapy strategies for certain genetic disorders or tumors, while also providing potential drug screening targets." (PMID 41378129, 2025).
infection (1 paper, 2014). The state of being infected such as from the introduction of a foreign agent such as serum, vaccine, antigenic substance or organism. "In up-regulated genes of head kidney samples, 2 genes respond to infection by D. pseudospathaceum-clone I (HYAL2, PRF1), 3 to clone XII (RGCC, CYP27B1, CCR9) and 6 to the clone mix treatment (ITGA5, SIX1, ATP1B3, MEF2C, MLF1, MYLPF)." (PMID 25254967, 2014).
MLF1 also shares sentences with these, for which no sentence is quoted: anaplastic large cell lymphoma (2 papers); Azoospermia (1); deafness (1); diffuse large B-cell lymphoma (1); Dystonia (1); Hypertension (1); male infertility (1); myelofibrosis (1); neuroendocrine tumors (1); oral squamous cell carcinoma (1); psychiatric disease (1); pulmonary fibrosis (1); stomach neoplasms (1); T-lymphoblastic lymphoma (1); type 2 diabetes (1); viral disease (1).